RETN (resistin)
Diseases named in the same sentence as RETN in open-access papers (continued):
Sharing a sentence is not in itself a finding about the gene and the disease.
Obesity (continued). "It is noteworthy that the biochemical assessment of adipokines, especially adiponectin and resistin, can provide relevant information to the monitoring and prognosis of people undergoing treatment for obesity." (PMID 38399430, 2024). "Circulating resistin levels have an emerging role as biomarkers for a variety of diseases, including glucose metabolism and obesity, diabetes, cancer, inflammatory diseases such as inflammatory bowel disease, and cardiovascular diseases." (PMID 38844967, 2024). "Apelin, vaspin and resistin are adipokines that play a crucial role in the pathophysiology of obesity." (PMID 39519480, 2024). "The mentioned effects of resistin, along with the finding that resistin activated the NF-кB transcription factor, supports the notion that macrophage signal cascades contribute to obesity and diabetes." (PMID 38227584, 2024). "We previously reported that resistin induces mitochondrial dysfunction, leading to obesity-induced metabolic diseases." (PMID 39050819, 2024). "Salivary resistin level alsodecreased in patients with obesity and periodontitis after therapy andchlorhexidine mouth rinse." (PMID 38597549, 2024). "Depending on the context, resistin appears to have both protective and detrimental effects to obesity-related hypertension, highlighting the complexity of resistin’s role in obesity and hypertension." (PMID 38615012, 2024). "Leptin and adiponectin are the most extensively studied adipokines in obesity-related cancers and there has been increasing interest in recent years toward new adipokines such as resistin and visfatin." (PMID 38255203, 2024). "Primarily, elevated resistin levels are correlated with obesity, reduced insulin sensitivity, and increased cardiovascular risk." (PMID 38263019, 2024). "A new label-free immunosensor wasdesigned for sensitivedetectionof resistin obesity biomarker in human biological fluids." (PMID 38395746, 2024). "In this study, matrix metalloproteinase 2 and resistin were found to be significantly different between the group of women with obesity and the group of women with normal body weight." (PMID 39769504, 2024). "Obesity primarily contributes to chronic low-grade inflammation by releasing a surge of signaling molecules, including the adipokines leptin and resistin, the cytokine interleukin-6 (IL-6), and the chemokine monocyte chemoattractant protein-1 (MCP-1)." (PMID 39717478, 2024). "Obesity induces dysregulated secretion of resistin, which is closely related to tumorigenesis in CRC, mainly via an inflammatory cascade." (PMID 39184804, 2024). "Firstly, it would be useful to study a population of children and adolescents with obesity for a period after the end of the intervention and investigate if the concentrations of apelin-12, vaspin and resistin, as well as the BMI, would remain stable." (PMID 39519480, 2024). "Despite these differences, resistin’s role in metabolic and CVD has been widely studied and is recognized as a key mediator of inflammation and metabolic disturbances associated with obesity and T2DM." (PMID 39682585, 2024). "In many aspects, the ECS and resistin share a common pathophysiology that includes obesity, inflammation, and glucose metabolism." (PMID 39050819, 2024). "MiR-155 not only interacts with other adipokines, but also downregulates resistin, whose levels are elevated in obesity and related disorders." (PMID 38541714, 2024). "Adipose tissue due to obesity can release several adipokines (including leptin, resistin, and adiponectin) as well as proinflammatory cytokines such as interleukin-1β, interleukin-6, and tumour necrosis factor-α." (PMID 38671417, 2024). "So far there are no studies on the connection between leukocyte and plasma expression of MMPs and TIMPs with inflammatory markers of obesity including circulating levels of resistin, AST, ALT and TNF-alpha." (PMID 38541059, 2024).
Obesity (continued). "Psoriasis and obesity share some cytokines with proinflammatory activity, like TNF-α, IL-1, and IL-6 and some adipokines (i.e., adiponectin, leptin, resistin, or lipocalin) with a pathogenic role in both diseases." (PMID 39062334, 2024). "Overall, it is evident that resistin contributes to the development of obesity-related complications." (PMID 39335642, 2024). "Along the same lines, in adults with obesity, resistin decreased after Roux-en-Y gastric bypass (RYGB) or adjustable gastric banding, as well as in adolescents with overweight or obesity after 8 months of intensive exercise." (PMID 39519480, 2024). "Meanwhile, the generation of adiponectin, leptin, visfatin, retinol binding protein-4 and resistin become irregularly and the production of free fatty acids begins to increase, then the obesity-related syndromes occurred and worsen." (PMID 38475734, 2024). "Resistin is a member of the adipokine family, is an adipocyte-secreted factor whose levels increase with obesity." (PMID 38238841, 2024). "Resistin is an adipokine that was originally discovered in 2001 by Dr. Mitchell Lazar's group as a link between diabetes and obesity, since then, it has emerged as a potential player in the pathogenesis of colorectal cancer (CRC)." (PMID 39184804, 2024). "Animal studies using transgenic mice have reported that obesity strongly suppresses resistin secretion." (PMID 38238841, 2024). "TNF-α, leptin, FFAs, and resistin are the components of adipose tissue remodeling in obesity that can contribute to oxidative stress-induced insulin resistance." (PMID 38892574, 2024). "Nonetheless, certain studies present contrasting results, and a definitive correlation between circulating resistin levels and obesity is yet to be established." (PMID 38263019, 2024). "Some components of adipokines, including leptin, adiponectin, resistin, Interleukin-6 (IL-6), and Tumor Necrosis Factor-α (TNF-α), have been associated with the development of insulin resistance, obesity, and related health conditions." (PMID 39457458, 2024). "Various other adipokines, including leptin, adiponectin, resistin, and visfatin, are secreted by adipose tissue and are elevated in obesity, contributing to the pathophysiology of obesity-related disorders, particularly in the development of DM type 2." (PMID 39273654, 2024). "For example, interventions targeting RETN have been shown to reduce inflammation and improve outcomes in diseases such as insulin resistance, obesity, and cardiovascular disorders." (PMID 39664590, 2024). "Previously, increased serum resistin levels were reported in rodent models of obesity, diabetes, and lung inflammation." (PMID 38338780, 2024). "Animal studies suggest that resistin has significant activities on insulin action, potentially linking obesity with insulin resistance." (PMID 38474226, 2024). "The relationship between serum resistin levels with insulin resistance, diabetes mellitus, and obesity in humans, however, remains controversial." (PMID 38474226, 2024). "Resistin, a protein suspected to be related to obesity and IR, is reportedly increased in children with central obesity." (PMID 36920931, 2023). "Lastly, resistin showed a tendency towards higher values in subjects with obesity than in individuals with normal weight." (PMID 38137540, 2023). "In mouse models of diet- and genetically-induced obesity, resistin levels in the blood are elevated relative to other proinflammatory adipokines, suggesting that high resistin levels are related to obesity and associated metabolic dysfunctions." (PMID 37238961, 2023). "In mice, circulating resistin levels are positively correlated to obesity and IR, and resistin-treated mice or resistin-overexpressing transgenic mice exhibit glucose intolerance and IR." (PMID 37283763, 2023).
Obesity (continued). "One meta-analysis of 15 studies confirmed that resistin levels are positively correlated with IR in patients with obesity or T2D, but only in those people presenting higher resistin levels in contrast to those with normal circulating levels." (PMID 37239098, 2023). "The presented work demonstrates that ApN and resistin, adipokines known to be altered during obesity, affect metabolic and cognitive functions." (PMID 37732123, 2023). "The name ‘resistin’ is coined from the original observation that it induces IR and has been proposed to link obesity and diabetes." (PMID 37283763, 2023). "For example, obesity-mediated hypertrophy of adipose tissue stimulates the secretion of leptin, resistin, and pro-inflammatory cytokines, which can induce ER stress, inflammation, and metabolic abnormalities in the liver." (PMID 37229466, 2023). "Intriguingly, resistin, a member of the adipokine family, is also a pro-inflammatory mediator that plays a critical role in the development of obesity, insulin resistance, and related comorbidities." (PMID 37798684, 2023). "Although there are reports that mouse adipocytes produce resistin, a debate about its link to insulin resistance and human obesity is ongoing." (PMID 37391843, 2023). "Firstly, six key adipokines known to be deregulated in obesity and related metabolic and vascular complications are described, namely adiponectin, leptin, resistin, IL-6, MCP-1 and PAI-1." (PMID 38136564, 2023). "Low levels of adiponectin are expressed in enhanced adiposity, while those of resistin and leptin have been found to be increased in obesity." (PMID 37371984, 2023). "The levels of serum visfatin, resistin and leptin in the obesity group were higher than those in other groups." (PMID 37231396, 2023). "In contrast, vaspin, as well as resistin, are thought to hold a compensatory role to overcome impaired metabolic states in obesity, while lower levels represent ameliorated IR, among others." (PMID 37239098, 2023). "One trial examining the correlation between circulating resistin concentrations and BMI, waist-to-hip ratio, or fat mass as markers of obesity showed a particularly strong correlation between resistin and anthropometric traits defining obesity." (PMID 37239098, 2023). "Obesity with visceral fat accumulation, which increases the levels of leptin, TNFα, IL-6 and resistin, and decreases the level of adiponectin, is related to cancer risk and mortality." (PMID 36879265, 2023). "Studies have indicated a relationship between high levels of circulating resistin with overweight and obesity." (PMID 38137922, 2023). "The development of IR caused by obesity is connected to the hormones and cytokines produced by adipocytes, including the rise of free fatty acids, TNF, leptin, resistin, and the inadequacy of adiponectin." (PMID 38045856, 2023). "Among various adipokines, adiponectin, leptin, resistin, and visfatin are considered to have the greatest relevance to obesity-related cancer." (PMID 36830834, 2023). "It has been observed that adolescents with obesity have higher values of resistin independently of their adipose tissue." (PMID 36376521, 2023). "Levels of resistin have been reported to be either increased, unchanged, or decreased in murine and human obesity and type II diabetes." (PMID 37149591, 2023). "During obesity, hypertrophic adipocytes release proinflammatory adipokines and cytokines, such as leptin, visfatin, resistin, MCP-1 and IL-6, which contribute not only to local but also systemic and liver inflammation." (PMID 37189422, 2023). "Since resistin is supposed to regulate glucose metabolism and is involved in obesity-induced T2D, hyperresistinemia has been declared as a biomarker for metabolic diseases." (PMID 37239098, 2023). "Nevertheless, the regulation of resistin gene expression in obesity needs further investigation because of controversial studies." (PMID 38136564, 2023).
Obesity (continued). "In obesity, there are observed higher levels of resistin, contributing to impaired insulin signaling and increased inflammation, which can further worsen metabolic dysfunction." (PMID 37629396, 2023). "Contrasting results on the levels of resistin have been reported in murine and human obesity and type II diabetes, but it is considered a possible link between adiposity and insulin resistance." (PMID 36674646, 2023). "Previous data have shown that serum and cerebrospinal fluid (CSF) levels of resistin are elevated in human and animal models of obesity and diabetes, implicating dysregulation of resistin in these diseases." (PMID 37935840, 2023). "Due to its pro-inflammatory nature, manifested by the activation of TNF-α, interleukins, and promotion of oxidative stress, resistin is considered to be involved in pathologies such as obesity, insulin resistance, neoplasia, and atherosclerosis." (PMID 37233709, 2023). "Specifically, when neurons were subjected to concentrations of resistin commonly encountered in obesity models, they exhibited a swift decrease in various metabolic parameters." (PMID 37834128, 2023). "The compound KSK-74 significantly compensates for metabolic disturbances that accompany obesity (plasma triglyceride, resistin, and leptin levels), improves glucose tolerance, and protects against adipocyte hypertrophy." (PMID 35806019, 2022). "Adipocytokines including ADPN, resistin, and LEP have been found to be associated with obesity, insulin resistance, β-cell dysfunction, endothelial dysfunction, dyslipidemia, and inflammation." (PMID 35418966, 2022). "Two hormones, leptin and resistin, are best known as adipose tissue-specific secretory factors, playing a critical role in obesity and diabetes." (PMID 36612600, 2022). "As confirmed by protein chip analyses, KY19334 decreased the expression levels of various adipokines such as angiopoietin‐3, DPP4, IGFBP‐5, leptin, resistin and PAI‐1, which are implicated in obesity‐related insulin resistance." (PMID 35384342, 2022). "Resistin is an adipokine playing an important role in inflammation and energy homeostasis, and is involved in the development of obesity, insulin resistance, and comorbidities, particularly atherosclerosis." (PMID 36499312, 2022). "In obesity, the endocrine function of adipocytes is changed, with decreased adiponectin and increased levels of leptin, resistin, IL-6, and tumor necrosis factor (TNF)." (PMID 36299943, 2022). "Certain studies have also concluded that adipokines such as resistin, leptin, and adiponectin have adverse effects on coronary arteriolar dilation in obesity which in turn is related to the development of coronary artery disease." (PMID 36299943, 2022). "In this way, it is possible to highlight the mechanisms of action of leptin, resistin, adiponectin, aromatase, IGF-1, and pro-inflammatory cytokines in cancers to characterize new associations between obesity and other neoplasias." (PMID 36262532, 2022). "Given its role in insulin resistance and inflammation, resistin is likely to explain, at least in part, the relationship between the inflammatory processes observed in obesity and metabolic diseases." (PMID 36457996, 2022). "Taking into account that chronic inflammation is a known cause of PCa, the chronic low-grade sub-clinical inflammation seen in obesity which often involves macrophage infiltration in the AT is accompanied by elevated levels of resistin." (PMID 35406450, 2022). "Resistin is a kind of adipokine that can resist insulin, increase blood sugar levels, and promote fat cell proliferation which facilitates obesity." (PMID 35418966, 2022). "Another important pro-inflammatory adipokine is Resistin, which is secreted by adipocytes and macrophages, and is thought to be a link between obesity and type 2 diabetes." (PMID 36465560, 2022).
Obesity (continued). "In our supplemental analysis, we found significant interactions in women between obesity status and sex hormone levels (p < 0.05 for leptin, resistin, and adiponectin)." (PMID 36712262, 2022). "The present study aims to determine the resistin levels of diabetic mothers with obesity and their effects on colostrum mononuclear cells." (PMID 36289594, 2022). "There are few reports regarding colostrum cells and resistin from mothers with obesity and diabetes." (PMID 36289594, 2022). "In their adipocytes, resistin decreases glucose transport in response to insulin, proposing a connection between obesity and insulin resistance." (PMID 35627631, 2022). "Obesity leads to an increase in the level of leptin and resistin and a decrease in the level of adiponectin in the serum." (PMID 36295052, 2022). "In obese subjects, when obesity is the result of both a high-calorie diet and genetic disorders, resistin concentration is higher than in lean individuals." (PMID 35453670, 2022). "Reportedly, adiponectin expression decreases with an increase in adiposity, but levels of leptin and resistin expression increase in obesity." (PMID 35806278, 2022). "The previous study has shown that resistin was increased in diet-induced obesity as well as in genetic models of obesity and insulin resistance." (PMID 36612600, 2022). "Breast milk contains adipokines such as resistin and leptin and is known for its protective effect against obesity and insulin resistance." (PMID 35225882, 2022). "Obesity results in significant changes in the adipokine profile, creating a shift towards elevated pro-inflammatory adipokines such as leptin and resistin and reduced levels of anti-inflammatory adipokines such as adiponectin and ZAG." (PMID 35909571, 2022). "Studies have shown that soyasapogenol B exerts anti-obesity and anti-diabetic effects on adipocytes via lowering cellular TG levels by accelerating TG lipolysis and reducing resistin secretion." (PMID 35983485, 2022). "Leptin and resistin play important roles in obesity and type II diabetes (T2D), and together with gastrointestinal ghrelin they regulate energy balance and body weight." (PMID 36135388, 2022). "The literature review used the Medline/PubMed and Google Scholar databases and the following keywords: resistin, epithelial ovarian cancer, and obesity." (PMID 35453670, 2022). "Recent studies have supported the use of the IL‐6R inhibitor tocilizumab, and the use of colchicine in COVID‐1947 was associated with the reduction of multiple inflammatory mediators, including CRP, IL‐6, resistin, and vascular proteins in obesity." (PMID 35837843, 2022). "Cross-sectional studies have demonstrated that, compared to lean individuals, those with obesity have higher resistin levels." (PMID 36466401, 2022). "A number of other adipocyte-derived mediators are increased during obesity, such as visfatin, resistin and apelin." (PMID 35844529, 2022). "Increased circulating leptin and resistin levels with decreased adiponectin levels are characteristics of obesity." (PMID 36500974, 2022). "The activities of resistin contribute to the emergence of diseases such as obesity, type 2 diabetes mellitus, atherosclerosis, and some types of neoplasms." (PMID 35453670, 2022). "For example, plasma resistin levels are positively correlated to obesity and IR in mice, and resistin neutralization using the leptin antibody improved IR in mice." (PMID 35740864, 2022). "The following keywords were used in different combinations for the literature search: obesity, adipokines, pathogenesis, leptin, resistin, visfatin, chemerin, DPP-4, adiponectin, omentin, isthmin, nesfatin, preparations, and clinical study." (PMID 36499312, 2022). "The resistin treatment reduced the percentage of cells expressing CD14+CD95+ (36.4 ± 9.2) in the colostrum from diabetic mothers with obesity." (PMID 36289594, 2022).